EPCAM (epithelial cell adhesion molecule)
Diseases named in the same sentence as EPCAM in open-access papers (continued):
Sharing a sentence is not in itself a finding about the gene and the disease.
cancer (continued). "Moreover, because EpCAM-based technologies for CTC detection are optimized for carcinoma, they are not appropriate for detecting CTCs derived from mesenchymal cancers (sarcoma, lymphoma, and neurogenic tumors)." (PMID 32764280, 2020). "EpCAM EV signal thus could not differentiate patients based on cancer stage but could distinguish patients with early stage PDAC from healthy controls." (PMID 31921310, 2019). "Currently, CD133, HER2, and EpCAM-directed CAR-T cells were proved to lyse CSCs in vitro and in vivo, indicating that the strategy of using CAR-T cells to eliminate CSCs could be a promising treatment for cancers." (PMID 31288857, 2019). "However, their specificity decreases if CTCs acquire a mesenchymal-like phenotype (including decreased surface expression of EpCAM) following the epithelial–mesenchymal transition and is low for CTCs derived from non-epithelial origin cancers (e.g., melanoma)." (PMID 31181790, 2019). "Additionally, with respect to the differentiation capacity of EpCAM-positive cancer cells, we showed that these cells can give rise to less tumorigenic EpCAM-negative cancer cells, attesting to the multi-lineage differentiation potential of these cells." (PMID 31261739, 2019). "Another reason for the high numbers of CCs described in this study might be the absence of EPCAM enrichment, allows inclusion of cancer cells undergoing epithelial–mesenchymal transition (EMT), and not just those with pure epithelial phenotype." (PMID 31319587, 2019). "However, EpCAM is not expressed on malignancies of non-epithelial origin, but is expressed on human epithelial malignant tumors, predominantly on adenocarcinomas." (PMID 31361893, 2019). "We then conducted survival analysis by protein levels of EpCAM regardless of the cancer subtypes." (PMID 29497050, 2018). "We demonstrated that the expression levels of the cancer stem-like cell markers CD44, OCT4, Nanog and ABCG2, as well as the EMT regulatory factor Slug were significantly enhanced in EpCAM-overexpressing cells and reduced in EpCAM-depleted HONE1 cells compared with control cells." (PMID 29305578, 2018). "Although CTCs have been mainly isolated from carcinomas through epithelial antigen-targeted antibodies (EpCAM), reports have demonstrated that EpCAM expression is not restricted to epithelial-derived tumors, but shared as well by CTCs isolated from patients with mesenchymal-derived cancers." (PMID 29707475, 2018). "EOC is unique among cancers in that cancer cells have diverse progenitors, ovarian surface epithelium (OSE) and fimbrial epithelia, that express common epithelial markers as keratins, EpCAM and E-cadherin as well as mesenchymal markers as vimentin and N-cadherin." (PMID 29854318, 2018). "PC3 target cells were treated with freshly isolated Peripheral Blood Mononuclear Cells (PBMCs) in the presence or absence of a BiTE that targets EpCAM, a surface protein expressed in many carcinomas and currently being evaluated as a therapeutic target in several clinical trials." (PMID 29499048, 2018). "Thus, a cross-regulatory role of EGFR and EpCAM appears as a general regulatory mechanism that is instrumental in carcinoma cells and includes negative and positive feedback loops to control ERK1/2 and, ultimately, cell fate." (PMID 30261040, 2018). "Additionally, an anti-EpCAM(scFv)–MAP fusion protein showed promising results with IC50 values of 43 and 67 nmol/L against L3.6pl and A431 EpCAM+ cancer cell lines, which is also comparably better when compared with that obtained for anti-EpCAM(scFv)–ETA’ (409 nmol/L on L3.6pl and 91 nmol/L on A431." (PMID 28653985, 2017). "Furthermore, over the past decade, EpCAM has been rediscovered as a CSC marker in colon, breast, hepatocellular, and pancreatic cancers, which makes it a potential molecular target for novel cancer therapy." (PMID 28574829, 2017).
cancer (continued). "In addition to EpCAM, Dt81Hepa1-6 cells express both CD24 and CD44 (data not shown), two markers of increased tumorigenicity that have also been associated with cancer stem cells." (PMID 28152020, 2017). "Therefore, the EpCAM aptamer-survivin siRNA chimera used in this study can effectively target both the cancer stem cells and non-cancer stem cells in vivo." (PMID 28724889, 2017). "The data from FGF19 expression with FGFR4 and EpCAM expression from the 24 immunohistochemically stained HCC sections were used to determine the correlation between FGF19 and its receptor FGFR4 and between the cancer stem cell marker EpCAM, respectively, in the ST-NASH-CR- HCC sequence." (PMID 27447573, 2016). "The present study reported, for the first time, that the coumarin-like compounds (Z3-Z5) extracted from M. paniculata could specifically inhibit epithelial cell adhesion molecule, namely EpCAM, without affecting cancer cell viability." (PMID 27480614, 2016). "In addition to EpCAM, a number of other biomarkers, such as CD133, CD44, CD24 and CD13, have been reported as biomarkers of HCC cancer stem cells, and it would be highly interesting to characterize cultured 3D spheroids for these stem cell markers in future studies." (PMID 26880118, 2016). "The reason might be that circulating epithelial cells (CECs), which are not cancer-related cells but express EpCAM, were included in collected CTCs32." (PMID 27892470, 2016). "Thus, the detection of EpCAM+ MPs by flow cytometry showed a better specificity and sensitivity than by ELISA (Sp: 96% vs 89%; Se: 79% vs 66%) to distinguish between carcinoma and non-carcinoma MPE." (PMID 26689993, 2016). "However, in vivo, putative carcinoma derived single positive taMPs (CD147+EpCAM−) levels were not significantly distributed in our study." (PMID 27127176, 2016). "EpCAM antigen is not expressed by all tumors, even not all carcinoma which may explains false negative results for tumoral-MPs detection despite the presence of tumoral cells by cytology." (PMID 26689993, 2016). "Petsch and coworkers showed variable amounts of EpEX in the serum of cancer patients and supposed that these quantities may not interact with systemically administered therapeutic EpCAM antibodies." (PMID 26296970, 2015). "Therefore, we targeted the EpCAM expressing cancer cells, using an EpCAM aptamer and SiEp loaded PEI nanocomplex, stabilized with sodium citrate for silencing EpCAM that can result in the inhibition of the cancer cell proliferation." (PMID 25576037, 2015). "Surprisingly, clinical trials of anti-EpCAM antibodies targeting the EpEx domain have shown limited efficacy in cancer therapy and its negative prognostic potential for survival of cancer patients remains unclear." (PMID 25695234, 2015). "Besides cancer cell line cells, absence of EpCAM on as high as 30 % of the examined 134 epithelial solid tumors was also reported." (PMID 26718583, 2015). "Higher EpCAM expression was correlated with stage III cancer, but not with stage I or II disease." (PMID 26356670, 2015). "Furthermore, an increasing fluorescence intensity was observed from borderline to cancer nest to metastatic tissues, revealing significant difference in EpCAM expression between cancer nest with and without metastasis (p < 0.05)." (PMID 26687301, 2015). "These EpCAM-negative CTCs may prove to be a very important subset of CTCs, since they are thought to represent stem cell-like cancer cells responsible for metastasis, and do not respond to current therapeutic regimens." (PMID 24879438, 2014). "Our preliminary results revealed that EpCAM-positive cells could be identified in the blood of cancer patients with this method, while no EpCAM+ or CD133+EpCAM+ cells could be found in healthy controls." (PMID 23959111, 2014).
cancer (continued). "In example, EpCAM-based exosome-capture technology is not selective, suffering from contamination of normal tissue-derived exosomes, because EpCAM is widely expressed among a variety of human epithelial tissues, cancers, progenitor and stem cells." (PMID 24424840, 2014). "Therefore, to investigate whether Lin28B is expressed in cancer stem cells, we performed magnetic cell sorting (MCS) to separate HCC cell lines into EpCAM+ and EpCAM- populations." (PMID 24244607, 2013). "Furthermore, miRNA fold changes observed between cancer and control plasma samples were improved when quantification on EpCAM+ exosomes rather than total plasma miRNA was carried out." (PMID 26082317, 2013). "The differences in the expression of these genes between the EPCAM+ and EPCAM− components of the PHT were qualitatively consistent with the differences in gene expression demonstrated by RNA-seq between the human carcinoma and murine stromal components of P2726-derived xenografts." (PMID 24278200, 2013). "All markers identifying cancer stem cells are surface markers such as epithelial cell adhesion molecule (EpCAM), CD44, CD24, CD133 and C-X-C chemokine receptor type 4 (CXCR4) definitely expressed on the normal stem cells at the same time and apparently changing during cancer stem cell development." (PMID 22452810, 2012). "EpCAM has been reported to have oncogenic potential and correlate with proliferation in cell lines; however, it is downregulated during EMT, and EMT markers have been shown to be more important than epithelial markers e.g., cytokeratin in predicting cancer progression." (PMID 22558290, 2012). "In order to evaluate if cancer cells might be lost in the non-enriched fraction, both the fractions (enriched for EpCAM-positive cells and non-enriched) were analyzed by flow cytometry." (PMID 21595914, 2011). "Moreover, treatment for 120 h with EpCAM-ReTARGTPRIFNαR149A inhibited the proliferative capacity of the cancer cell lines OvCAR3 and PC3M by ~91% without compromising the viability of the TPR-specific CD8pos T cells and increased their capacity for IFNγ secretion." (PMID 40243928, 2025). "However, recent studies have revealed low or absent EpCAM expression in certain cancers." (PMID 39337304, 2024). "However, EpCAM targeting has not been applied to the treatment of non-cancer diseases." (PMID 38791091, 2024). "It is worth noting that underivatized mAb may not be sufficient for effective cancer therapy; as reflected in our findings, alternative approaches such as bispecific anti-EpCAM/anti-CD3 antibodies and ADCs face challenges with stability, specificity, and toxicity in clinical trials." (PMID 39595576, 2024). "However, healthy simple and pseudostratified epithelia in humans express EpCAM in basolateral membranes with the exception of hepatocytes and keratinocytes in contrast to the ubiquitous non-polarized overexpression profile in epithelial cancer cells." (PMID 36845124, 2023). "Thus, it is not surprising that the role of EpCAM in cancers is highly context dependent." (PMID 36369033, 2022). "However, the fast development of large numbers of resistant clones under AKT/mTOR therapy observed in vitro and in the orthotopic xenotransplantation mouse model in vivo strongly suggests that this therapy alone will not be sufficient to eliminate EpCAM+ or CD90+ cancer stem cells from HCC patients." (PMID 35454789, 2022). "Consequently, cancer patients might benefit from approaches targeting HGF/c-Met and EpCAM." (PMID 35986321, 2022).
cancer (continued). "Epithelial cell adhesion molecule (EpCAM)high integrin subunit alpha 6 (CD49f)+ luminal progenitors (LPs) and EpCAMlow/−CD49f+ basal cells (BCs) were isolated from reduction mammoplasty samples from 3 cancer-free non-carriers or prophylactic mastectomies obtained from 3 BRCA1-mutant donors." (PMID 35459234, 2022). "However, EpCAM is not found in non-epithelial cells or cancers of non-epithelial origin." (PMID 34790117, 2021). "However, this previous ESCC studies using EpCAM-based CTC isolation strategy may underestimate the highly heterogeneous CTC population, and might miss those aggressive refractory CTCs undergoing EMT or CTCs, with cancer stemness properties." (PMID 32466419, 2020). "Of note, cancer patient-derived and noncancer patient-derived EpCAM+ cells could be clearly separated using the overall gene expression as well as epithelial and B cell-annotated genes—with the exception of one M0-stage cell, which was therefore excluded from further analysis." (PMID 33020483, 2020). "Thus, HNSCC is not considered as an exclusively EpCAM positive type of cancer." (PMID 32300118, 2020). "Moreover, as reported, this method could be directly transformed to a diagnostic platform through the detection of disease-specific markers (e.g., EpCAM, CD133, EGFR for cancer cells) on the isolated exosomes, facilitated by disease-specific antibody and magnetically activated cell sorting." (PMID 32206116, 2020). "Thus far, the contribution of EpCAM in BC cellular plasticity, and altered phenotypic regulations such as radioresistance, stemness and further how these phenotypes ultimately impact the metastatic property of cancer cells is not yet established." (PMID 33490064, 2020). "Thus, the clinical detection of metastasis-competent EpCAM+ CTCs might not be limited by EMT, at least in cancer types/subtypes where EpCAM expression is strongly associated with cancer progression." (PMID 32764280, 2020). "However, due to the high variety of cancer types and subtypes, metastasis formation might not always require EpCAM expression." (PMID 32764280, 2020). "However, these EpCAM antibodies have never been used in conjunction with PIT, which could mediate cytotoxicity in the EpCAM positive cancer cells without inducing pancreatic side-effects." (PMID 30140380, 2018). "However, some cancer cells have little or no EpCAM expression." (PMID 27013581, 2016). "When epithelial cancer cells were analysed after being sorted with FACS as EpCAM + cells from cultured cancer cell lines they were found positive for Ig mRNA but no Ig protein expression could be detected in flow cytometry, indicating very low protein expression of IgA." (PMID 23637900, 2013). "In addition, we show that the treatment of TPR/IL2-expanded PBMCs with EpCAM-ReTARGTPRIFNαR149A in the absence of cancer cells promotes T-cell viability and persistence and increases the number of viable T cells from 4 × 105 up to 6 × 105 cells/mL compared to treatment with EpCAM-ReTARGTPR." (PMID 40243928, 2025). "Secretion of the pro-inflammatory cytokine EpCAM, which was up-regulated in the astrocytes and GBM011 cells upon incubation with hEVs, drives carcinoma invasion but its role in GB progression is not well understood." (PMID 39767739, 2024). "Results indicated that using both EpCAM and vimentin antibodies significantly improved CTC isolation compared to using either marker alone, regardless of cancer stage." (PMID 37345161, 2023). "The outcomes showed that in the majority of cancer cases, LIPT2 expression was eminently positively correlated with MKI67, PCNA, BCL2, BAX, and EPCAM, while showing a significant negative correlation with VIM." (PMID 38129565, 2023). "Despite the non-detection of EpCAM-negative cells, a green Alexa Fluor 488 fluorescence was detected in EpCAM+ cells, indicating a WT1 expression in cancer cells." (PMID 36293034, 2022).
cancer (continued). "In contrast, the triple negative (HER2‐/ER‐/PR‐) MDA MB231 cells showed negligible fluorescent signal for HER2, ER, and PR, but were positive for cancer markers (EGFR (not shown) and MUC1 and EpCAM)." (PMID 35508767, 2022). "As there is no universal biomarker for cancer, we compared the CTC detection efficiency in each solid tumor with EpCAM or CSV antibody." (PMID 33717672, 2021). "Since an anti-EpCAM CAR was introduced in the iNK cells, cancer cell lines with EpCAM expression (BT474 and HTB131) and without EpCAM-expression (MCF7 and HTB129) were chosen as targets for this cytotoxicity assay." (PMID 34802459, 2021). "Cho and coworkers (2019) found that miR-21, miR-574-3p, EpCAM, and epidermal growth factor receptor (EGFR) were more highly expressed in exosomal cancer-derived cells than in noncancer cells." (PMID 34940275, 2021). "Three types of cancer cell lines were selected to demonstrate the usefulness of our system: SK-BR-3 as high-, HCC1569DP as medium-, and A549TT as no-EpCAM-expressing cell lines." (PMID 32790768, 2020). "UWG01CTC had no detectable EpCAM, mesenchymal (NCAD, Vimentin), or cancer stem cell marker (CD44, CD133, ALDH1)." (PMID 31953491, 2020). "Tumors had no significant change in cancer stem cell enrichment marker CD44+CD24−, but tumors from the obASC group showed decreased expression of CD326 (epithelial cell adhesion molecule)." (PMID 31118047, 2019). "The rationale for such an approach is the assumption that all cells in the blood expressing epithelial features (EpCAM-positive) and not expressing pan-leukocyte antigens (CD45-negative) are cancer cells." (PMID 31146464, 2019). "Organoids were shown to originate from epithelial cancer cells by staining with antibodies to EpCAM, a positive cancer cell marker, and CD45, a macrophage marker not expressed by cancer cells." (PMID 31572675, 2019). "The expression of cancer stem cell surface markers, such as CD133, CD44, or EpCam, was not influenced by salinomycin treatment." (PMID 30763370, 2019). "CSCs were isolated based on triple marker-positive status (CD44+/CD133+/EpCAM+); and isolated non-CSC bulk cancer cells expressed none of these cell surface protein markers; i.e., triple marker-negative (CD44/CD133/EpCAM)." (PMID 28281569, 2017). "Univariate and multivariate analysis verified that the CTC (CK/EpCAM+CD45−), but not other cell populations, is a significant and independent biomarker for cancer patients (p < 0.01)." (PMID 28481895, 2017). "Moreover, nuclear localization of β-catenin was also observed in the EpCAM+ cells These results may explain the two different immunohistochemical expression patterns of YB-1 in human HCC and revealed that YB-1 exerted its specific functions in cancer initiating cells via DNA transcription." (PMID 27911878, 2017). "CTCs represent very heterogeneous populations of tumorigenic cancer cells in MBC patient and some subpopulations had undergone EMT, which expressed decreased level or absence of epithelial markers including EpCAM." (PMID 27706044, 2016). "The overall positive (PPV) and negative predictivevalues (NPV) across the investigated cancer entities (NSCLC, CRC and PaCa) for EpCAM+ taMP were: 79.03% (PPV) and 85.29% (NPV), respectively, with an overall sensitivity of 95.15% and specificity of 52.73%." (PMID 27127176, 2016). "While other antibodies can be added to EpCAM antibody to make a cocktail for increased CTC capture rate, including EMT cells, an ideal cell surface biomarker to distinguish cancer cells from normal mononuclear cells is not available." (PMID 26397728, 2015).